EGFR (epidermal growth factor receptor)
Diseases named in the same sentence as EGFR in open-access papers (continued):
Sharing a sentence is not in itself a finding about the gene and the disease.
cancer (continued). "This suggests that the failure of EGFR-based cancer treatment may be partly attributed to ENAH-mediated AKT activation." (PMID 39511483, 2024). "For instance, cetuximab, a monoclonal antibody (mAb) that binds to the epidermal growth factor receptor (EGFR), which is typically overexpressed by several cancer types, has been recently developed into a version conjugated to IR700, a photosensitizer that absorbs light at 690 nm." (PMID 38256096, 2024). "The distribution of EGFR partner genes in each cancer species is also scattered, which may introduce challenges for the widespread detection of partners." (PMID 39054543, 2024). "It effectively diminished cancer cell viability, induced DNA damage, halted cell cycle progression, generated reactive oxygen species (ROS), impaired mitochondrial transmembrane potential, instigated apoptosis and successfully inhibited EGFR‐TKD." (PMID 38685671, 2024). "Drugs targeting EGFR have achieved remarkable success in cancer treatment." (PMID 39404930, 2024). "EGFR is an important membrane-bound receptor that is extensively expressed in many cells and has become a prominent target for therapeutic applications in some diseases and cancer therapy." (PMID 39213375, 2024). "With EGF/EGFR hypo‐methylation accelerating cancer growth by activating EGFR pathway." (PMID 39036344, 2024). "These EGFR-stabilizing proteins are also promising targets for EGFR-overactivated cancer treatment." (PMID 38745775, 2024). "It was reported that inactivation of neurofibromin 2 renders cancer cells susceptible to ferroptosis through inhibiting YAP/TAZ signaling, whereas activation of epidermal growth factor receptor (EGFR) and isocitrate dehydrogenase 1 promote ferroptosis by inhibiting SLC7A11 and GPX4, respectively." (PMID 39568772, 2024). "The most significantly enriched pathways of HSPcluster-B are associated with cancer and inflammatory responses, including type II interferon to JAK-STAT signaling pathway, IL10 family to JAK-STAT signaling pathway, EGF EGFR PI3K NFKB signaling pathway, and TNF NFKB signaling pathway." (PMID 39430254, 2024). "However, EGFR is overexpressed in a high percentage (50–70%) of MPM patients, and a cancer-driving role of EGFR has been already shown for this cancer." (PMID 39300217, 2024). "EGFR-induced activation of PI3K/Akt pathway plays a key role in GBM cancer cell survival." (PMID 39001381, 2024). "Based on our results, we could hypothesize that FPRs/uPAR crosstalk is crucial in chronic inflammation, while uPAR’s binding to VN and its crosstalk with EGFR is preferentially used by cancer cells to proliferate." (PMID 38542130, 2024). "In addition, the 64Cu-Dox-immunoliposomes exhibited EGFR-specific binding to target cancer cells (A431 and A549) with the least off-target binding (MDA-MB-453)." (PMID 38339090, 2024). "EGFR’s pivotal role in cancer progression makes it a primary target for therapeutic intervention." (PMID 38474160, 2024). "Moreover, it was discovered that FZYA inhibited the pedigree transformation among cancer subtypes due to EGFR-TKI treatment." (PMID 39735556, 2024). "Moreover, the downregulation of EGFR expression highlights the potential of the compound to interfere with crucial signalling pathways involved in cancer progression." (PMID 38770462, 2024).
cancer (continued). "The molecular mechanism of the effect of EET on cancer cell proliferation is achieved in part through significantly enhanced phosphorylation of the epidermal growth factor receptor (EGFR) and the activation of downstream signalling cascades, including the MAPK and PI3K/Akt pathways." (PMID 38523633, 2024). "When EGFR undergoes mutations or amplification, the EGFR-AKT-TSPAN8-STAT3 axis becomes hyperactivated, resulting in an aggressive phenotype and poor prognosis of cancer." (PMID 39469621, 2024). "Furthermore, the inhibition of EGFR expression has been reported to suppress EMT in cancer cells via the upregulation of SNAIL." (PMID 38338029, 2024). "Thus, the design of therapeutic mAbs, such as cetuximab, that target EGFR has led to improvements in the outcome of cancer patients." (PMID 39051331, 2024). "Additionally, cellular processes such as the epithelial-to-mesenchymal transition further complicate the resistance scenario by reducing the cancer cells’ reliance on EGFR signaling." (PMID 38790167, 2024). "The accumulation of EGFR in the cytoplasm was noted consistently and was in agreement with prior findings that emerged from the treatment of various EGFR mutant cancers with Tyr kinase inhibitors where the cytoplasmic accumulation of EGFR was used as a predictor of clinical efficacy." (PMID 39268460, 2024). "Indeed, small molecule EGFR inhibitors such as Gefitinib and Erlinotib have been clinically used in cancer chemotherapy since their FDA approval in the early 2000s." (PMID 39234105, 2024). "The HER family, particularly EGFR and HER2, has also been implicated in various cancers." (PMID 38601214, 2024). "Therefore, U3-1402 is an excellent treatment option for patients with HER3+ cancers and is undergoing a phase III trial in EGFR-mutated NSCLC." (PMID 38835349, 2024). "Cetuximab, a chimerized monoclonal antibody to EGFR, specifically bind to the EGFR with high affinity by occluding the ligand-binding region, blocking ligand-induced EGFR tyrosine kinase activation and subsequent signal-transduction events leading to cancer cell proliferation." (PMID 38302471, 2024). "Epidermal growth factor receptor inhibitors (EGFRi) are approved for treating various cancers." (PMID 39624566, 2024). "Additionally, factors like Epidermal Growth Factor Receptor (EGFR) gene activity can lead to the increased methylation (silencing) of NRY genes in certain cancers." (PMID 39594721, 2024). "EGFR can promote cell proliferation, survival, angiogenesis and metastasis in various cancers." (PMID 39199664, 2024). "Aberrant EGFR signaling drives tumorigenesis and cancer progression." (PMID 39000275, 2024). "RNF144A maintains EGFR signaling to encourage cancer cell proliferation that is dependent on EGF." (PMID 38313020, 2024). "Moreover, nuclear EGFR has been shown to contribute to resistance to various cancer therapies, such as radiation, cisplatin, and cetuximab." (PMID 38820302, 2024). "In another study, cetuximab which is an EGFR inhibitor is also bound to the domain III67 suggesting that these HIV protease inhibitors might be used in cancer treatment." (PMID 38216592, 2024). "EGFR signaling is dysregulated in various cancers, including PCa." (PMID 38956591, 2024). "The analysis revealed that the pathways that may play a role were mainly cancer pathway, EGFR tyrosine kinase inhibitor resistance, PPAR signaling pathway, Rap1 signaling pathway, PI3K-Akt signaling pathway, etc.." (PMID 38515732, 2024).
cancer (continued). "The anti-EGFR x anti-CD3 LiTE specifically activates and redirects polyclonal mouse T cells to kill EGFR-positive cancer cells, while the Albu-LiTCo combines PD-L1/PD-1 axis blockade with PD-L1-dependent 4-1BB costimulation and enhances EGFR-specific LiTE T cell-mediated activation in vitro." (PMID 39835115, 2024). "This suggests that targeting RCC1 might have potential in combinatory therapy with first-line anti-cancer drugs like EGFR inhibitors, mTOR inhibitors and AR inhibitors, whose effectiveness are often compromised by increased cytoplasmic distribution of Skp2." (PMID 38561375, 2024). "A randomised controlled phase III trial of 80 cancer patients treated with EGFR inhibitors showed that the application of EGF ointment twice daily significantly improved skin toxicities (77.8% response rate using 20 ppm EGF concentration) and patient quality of life." (PMID 39061166, 2024). "EGFR is associated with cell survival, differentiation, and proliferation as it binds to its ligand, EGF, whose structural activation promotes various human cancers metastasizing." (PMID 38965548, 2024). "By selecting a cell cycle–targeted inhibitor, and cetuximab to direct the payload to EGFR-expressing cancer cells, we generated cetuximab–SNS-032 ADC, bearing a small fraction of the drug alone dose required to engender antitumor effects, and we evaluated this as a treatment against TNBC." (PMID 38772416, 2024). "The eight major pathways of DEGs in the downregulated genes were associated with the Ras signaling pathway, MAPK signaling pathway, pathway in cancer, drug metabolism, cellular senescence, ErbB signaling pathway, EGFR tyrosine kinase inhibitor (TKI) resistance, and AMPK signaling pathway." (PMID 39075471, 2024). "Following a variety of stressors, EGFR is known to be inactivated by intracellular trafficking, including being internalized to the early endosome and lysosome following oxidative stress and hypoxia in cancer cells." (PMID 38467653, 2024). "HER3 antibodies can be involved in cancer treatment in combination with compounds targeting EGFR and HER2, endocrine therapeutic agents, and chemotherapeutic agents, but led to resistance to some therapies, including targeted therapy, chemotherapy, radiotherapy, and hormone therapy." (PMID 38835349, 2024). "The inhibition of EGFR expression in cancer cells could inhibit the epidermal growth factor that induces increased proliferation, migration, and apoptosis." (PMID 38338029, 2024). "It has been reported that, in some cases, changes in EGFR levels alone may be sufficient to induce cancer development." (PMID 38324801, 2024). "Losatuxizumab-vedotin is an ADC targeting EGFR found on cancer cells." (PMID 39456611, 2024). "EGFR targeting has become a viable approach in the development of anti-cancer medications." (PMID 39652601, 2024). "While RAS status is typically assessed prior to the initiation of systemic chemotherapy, most patients develop acquired resistance even after an initial response to chemotherapy containing anti-EGFR mAb, indicating changes in cancer clones and/or genetic status." (PMID 39066951, 2024). "Additionally, the identification of the epidermal growth factor receptor (EGFR) as a critical downstream target emphasizes NAT10′s role in cancer progression by modulating essential cellular pathways." (PMID 39061374, 2024). "For instance, identifying signals activated only in wound environments, such as Piezo1-induced EGFR signaling may provide better targets for cancer." (PMID 39636982, 2024).
cancer (continued). "Further research on ZNRF3/RNF43 regulation of EGFR versus WNT receptors in different cancer stages can contribute to a comprehensive understanding of RSPO-ZNRF3/RNF43 signaling in cancer progression and provide valuable knowledge for potential therapeutic interventions." (PMID 38260423, 2024). "However, in EGFR-amplified cancers, the disruption of this bond in multiple EGFR copies reduces this steric hindrance, making the epitope accessible in the untethered EGFR7." (PMID 38830977, 2024). "By targeting drug-resistant EGFR mutations and leveraging the potential of NGS technologies, we aim to pave the way for more personalized and effective treatments, ultimately improving outcomes and quality of life for those affected by EGFR-driven NSCLC cancers." (PMID 39130636, 2024). "Thus, our findings attributed LAMC2 to a new function in promoting EGFR translation across different cancer cell lines." (PMID 38526177, 2024). "The EGFR signaling cascade serves as a pivotal regulator in various cellular processes, including proliferation, differentiation, division, survival, and the development of cancer." (PMID 38632608, 2024). "Generally, Nrf2 activation is a negative prognostic factor in cancer; indeed, it is involved in several key cancer-supportive functions, including cancer cells proliferation through the upregulation of anabolic metabolism and by acting on epidermal growth factor receptor signaling." (PMID 39769005, 2024). "Early attempts at using BRAF inhibitors such as vemurafenib, which has been successful in treating BRAF-mutant melanoma, showed limited efficacy in CRC, mostly due to rapid reactivation of EGFR signaling, a compensatory mechanism that allows cancer cells to bypass BRAF inhibition." (PMID 39684219, 2024). "Strategies aimed at inhibiting EGFR nuclear translocation hold promise for improving overall survival rates, underscoring the importance of targeting intracellular trafficking pathways of EGFR in cancer treatment." (PMID 39404930, 2024). "Theoretically, the blockade of EGFR must effectively abrogate the proliferation of cancer cells." (PMID 38532948, 2024). "EGCG promotes apoptosis in cancer cells through various mechanisms, including the inhibition of the Epidermal Growth Factor receptor (EGFR), the activation of caspase (specifically, caspase 9, 8, and 3), and the upregulation of pro-apoptotic proteins such as Bax." (PMID 39858410, 2024). "Based on these facts, we investigated whether co-culture with HUVECs affects EGFR TKI resistance in cancer cells and whether HAT can counteract this process." (PMID 38338342, 2024). "On the other hand, EGFR has eight residues at the interface where cancer mutations are observed, but none of them are predicted to be deleterious by SIFT." (PMID 38216592, 2024). "In addition, HER2 amplification has been identified as an acquired resistance mechanism in EGFR-mutant NSCLC cancers treated with EGFR inhibitors, occurring in approximately 15% of patients resistant to EGFR TKIs." (PMID 38893138, 2024). "Furthermore, DCs can be engineered to express membrane-bound cytokines to target their receptors, such as EGFR, on cancer cells." (PMID 39105847, 2024). "EGFR is a protein that can contribute to the growth of cancer cells when overactive." (PMID 38399423, 2024). "Finally, elevated EGFR or ErbB2 levels sensitize cancer cells to ferroptosis-inducing treatment in a mouse xenograft model." (PMID 39604370, 2024). "This discussion delves into the fundamental aspects of EGFR inhibitors in cancer treatment." (PMID 38611728, 2024). "Our results propose an alternative approach to inhibit EGFR-mediated signaling, which could be considered for those cancer conditions in which receptor activation is mainly triggered by HBEGF." (PMID 39329717, 2024).
cancer (continued). "However, due to the limitations in organoid models in replicating precise human cancer TME and the potential influence of specific EGFR mutations, further in vivo studies and clinical trials are necessary for validation." (PMID 39766891, 2024). "EGFR plays a critical role in the development and progression of various cancers." (PMID 39130636, 2024). "Moreover, based on GSEA analysis from the RNA‐sequencing database, epithelial to mesenchymal transition (EMT), coagulation, and angiogenesis, the three major characteristics related to malignant tumors, decreased in PAICS deficiency EGFR wild‐type NSCLC cells." (PMID 38463398, 2024). "Interestingly, miR-7 upregulation, through targeting various signaling pathways like EGFR or FAK, is linked to the reversal of the transition from epithelial to mesenchymal cells in cancer of the liver, ovary, or breast." (PMID 39233736, 2024). "Further work should explore the extent to which EGFR and WNT receptors (Frizzled and LRP5/6) each transmit the effect of ZNRF3/RNF43 deactivation at different cancer stages and investigate the efficacy of blocking both EGFR and WNT signaling in treatment of ZNRF3/RNF43-deactivated tumors." (PMID 38260423, 2024). "Additionally, trametinib can provoke acneiform eruptions similar to those triggered by cetuximab, another cancer treatment targeting the epidermal growth factor receptor." (PMID 39328691, 2024). "As observed for ctDNA, the presence of KRAS or EGFR mutations in cancer specimens was not correlated with OS (HR = 0.65, 95% CI = 0.32–1.31, P = 0.211; and HR = 0.54, 95% CI = 0.21–1.39, P = 0.168)." (PMID 37973956, 2024). "This approach seeks to achieve a synergistic effect by combining immunotherapy to enhance the immune system’s targeting of cancer cells, encorafenib to inhibit the cancer-driving BRAF V600E mutation, and cetuximab to target the often overactivated EGFR pathway in colorectal cancer." (PMID 38790167, 2024). "The strong binding interactions suggest that these compounds could significantly disrupt EGFR signaling pathways, thereby inhibiting cancer cell proliferation." (PMID 39194519, 2024). "Additionally, many components of cancer gene signaling pathways, such as EGFR, RAS, and RAC, are localized to endocytic vesicles or adhesion sites." (PMID 38189823, 2024). "The EGFR was shown to be overexpressed in different cancer forms." (PMID 38339275, 2024). "In HBEGF-dependent cancers this alternative approach could be considered to overcome the drug resistance frequently observed following the use of conventional EGFR tyrosine kinase inhibitors." (PMID 39329717, 2024). "Additionally, we substantiated our findings in multiple cell lines, human cancer cell xenograft models, and genetically engineered mouse models, wherein the loss of ZNRF3/RNF43 resulted in elevated EGFR levels and facilitated cancer progression." (PMID 38260423, 2024). "It’s worth noting, however, that off-target resistance (e.g., Ras, EGFR) might make the cancer more oncogenic and aggressive, as reviewed in the 2002 Nature Rev Cancer paper." (PMID 38188499, 2024). "NIR-PIT targeting EGFR-expressing cancer cells has been approved for clinical use in Japan (Rakuten Medical Inc.)and is currently in Phase 3 clinical trials in the United States (ClinicalTrials.gov Identifier: NCT02422979), indicating a promising level of safety and efficacy in humans." (PMID 38275890, 2024). "The obtained exosomes could redirect and activate cytotoxic T cells to cancer cells to produce cancer-killing effects, not only inducing T cells to cross-link with EGFR-expressing breast cancer cells but also triggering effective antitumor immunity." (PMID 38835784, 2024). "In OSCC, EGFR overexpression was correlated with EMT-mediated cancer metastasis." (PMID 38263290, 2024).